BASP1 (brain abundant membrane attached signal protein 1)
Diseases named in the same sentence as BASP1 in open-access papers (continued):
Sharing a sentence is not in itself a finding about the gene and the disease.
BASP1 also shares sentences with these, for which no sentence is quoted: lymphoma (3 papers); stomach carcinoma (2); abdominal aortic aneurysm (1); acute lymphocytic leukaemia (1); acute promyelocytic leukemia (1); ankylosing spondylitis (1); anorexia nervosa (1); benign tumours (1); bipolar disorder (1); cardiac hypertrophy (1); cervical adenocarcinoma (1); cholangiocarcinoma (1); Chronic myelogenous leukaemia (1); colorectal cancer (1); esophageal cancer (1); hypertensive nephropathies (1); insulinoma (1); kidney cancer (1); liver cancer (1); movement disorder (1); neuroblastoma (1); non-small cell lung carcinoma (1); sarcoma (1); schizophrenia (1); Sepsis (1); small cell lung carcinoma (1); thyroid tumor (1); type 2 diabetes (1); Vestibular schwannoma (1).